ERBB2 (erb-b2 receptor tyrosine kinase 2)
Diseases named in the same sentence as ERBB2 in open-access papers (continued):
Sharing a sentence is not in itself a finding about the gene and the disease.
breast cancer (continued). "In this cohort study of 1 136 016 patients from the National Cancer Database in the US, the proportions of ERBB2-low breast cancer were slightly lower among Hispanic and non-Hispanic Black patients compared with non-Hispanic White patients." (PMID 36821125, 2023). "HER2 (also known as ERBB2/neu) is a tyrosine kinase transmembrane receptor of the plHER family (EGFR/HER1, HER2, HER3, and HER4), which is amplified and/or overexpressed in various cancer types, including early-stage breast cancer." (PMID 37896184, 2023). "The proof of principle has already been provided decades ago when amplifications of 17q in a subset of breast cancer genes were revealed to harbor ERBB2 amplifications and became the basis for effective therapies that have changed the outcomes of HER2-positive breast cancers." (PMID 36902501, 2023). "The dependency evaluation of the cell lines with SCRIB, VANGL2 and NOS1AP amplifications with CRISPR and RNAi revealed several genes involved in breast cancer pathogenesis, such as FOXA1, ERBB2, PIK3CA and CDK4, to be among the top preferential essential genes." (PMID 36675340, 2023). "Another important difference between human and canine breast cancer is the overexpression of ERBB2, which is exclusively found in the human breast cancer HER-2+ subtype and is not yet identified in canine mammary carcinoma." (PMID 37835752, 2023). "Our findings also show that the EP regimen was an effective adjuvant chemotherapy regimen for women with ERBB2-negative breast cancer." (PMID 36826820, 2023). "Moving forward, the availability and use of ERBB2-directed antibody-drug conjugates will likely drive prognosis in ERBB2-low disease, rather than intrinsic differences in biology between ERBB2-low and ERBB2-negative breast cancer." (PMID 36821125, 2023). "The study identified 1 136 016 patients (mean [SD] age, 62.4 [13.1] years; 99.1% female; 78.6% non-Hispanic White), of whom 392 246 (34.5%) were diagnosed with ERBB2-negative and 743 770 (65.5%) with ERBB2-low breast cancer." (PMID 36821125, 2023). "No alterations in key actionable genes including ERBB2 (HER2), NTRK fusions, or PIK3CA mutations were identified in breast cancer patients." (PMID 35648382, 2023). "First, a substantial proportion of patients included in the CALGB 40601 and PAMELA trials received trastuzumab combined with lapatinib, a dual treatment used in the metastatic setting but not approved for early-stage ERBB2/HER2-positive breast cancer." (PMID 36602784, 2023). "Those that have ERBB2 gene amplification with or without HR expression are called HER2-positive (HER2+) breast cancer, which accounts for 20–25% of all cases." (PMID 37237509, 2023). "Recently, three CDK4/6i (palbociclib, abemaciclib, and ribociclib) have received FDA approval to treat estrogen receptor (ER)-positive, Erb-B2 Receptor Tyrosine Kinase 2 (HER2)-negative advanced breast cancer in combination with endocrine therapy." (PMID 37452037, 2023). "Its expression defines a clinically challenging form of an aggressive breast cancer, which is non-responsive to the standard ErbB2-targeting immunotherapy with trastuzumab and pertuzumab because it lacks their binding sites." (PMID 37420029, 2023). "In detail, tucatinib is an inhibitor of the human epidermal growth factor receptor tyrosine kinase ErbB-2 (also called HER2) used in combination with other medications (i.e., trastuzumab and capecitabine) to treat unresectable or metastatic HER-2-positive breast cancer." (PMID 37896171, 2023). "Surprisingly, our data found that endocrine resistance pathways, which could be divided into 3 functional categories, ERBB2, BCL2, and CCND1, were upregulated in FA-derived breast cancer compared to FA component." (PMID 37328469, 2023). "Also known as ErbB2 or CD340, HER2 regulates cell growth and proliferation and is one of the most used surface receptors to target liposomes for breast cancer and others, such as prostate cancer." (PMID 36678845, 2023).
breast cancer (continued). "In the larger dataset of metastatic tumor tissue from patients with ERBB2 non-amplified breast cancer, however, this finding was statistically significant [22 of 405 samples (5.4%) vs 15 of 115 samples (13.0%), p = 0.0119]." (PMID 37101291, 2023). "In this cohort study of patients with breast cancer receiving NACT, Black patients had a lower pCR rate for triple-negative and HR−/ERBB2+ breast cancer but a higher pCR rate for HR+/ERBB2− diseases, whereas Asian and Pacific Islander patients had a higher pCR rate for HR−/ERBB2+ diseases." (PMID 36995711, 2023). "In this study, the EP regimen was noninferior to the EC-P regimen and was an effective adjuvant chemotherapy regimen for women with ERBB2-negative breast cancer." (PMID 36826820, 2023). "Monoclonal antibodies against human epidermal growth factor receptor 2 (HER2; also known as ErbB2), e.g., trastuzumab and pertuzumab, are widely used in HER2-positive breast cancer and more recently also in other HER2-positive cancer types such as gastro-intestinal tumours." (PMID 37240854, 2023). "In this cohort study of 690 patients with early-stage breast cancer, Black patients with hormone receptor–negative/ERBB2+ disease had significantly lower odds of achieving pathological complete response compared with White patients." (PMID 36995716, 2023). "Triple-negative breast cancer (TNBC) represents 15% of breast carcinomas and is defined by the absence of the three main breast cancer biomarkers—estrogen receptors, progesterone receptors, and HER2 (also known as ERBB2)." (PMID 37954205, 2023). "Although these tumors mostly consisted of HER2-enriched tumors and mimicked HER2-positive breast cancers, no significant overexpression, gain/amplification or elevated mutation rate was discovered for ERBB2." (PMID 37607916, 2023). "Historically breast cancer has been classified into three subtypes based on the expression of estrogen (ER) or progesterone (PR) hormone receptors and human epidermal growth factor receptor 2 (HER2/ERBB2)." (PMID 36982548, 2023). "Given that EphA2 can interact with HER2 (also named ErbB2) and cooperate with HER2 to activate ERK signaling, we concluded that RNF5 inhibition decreases ERK and Akt activation through the increase in the EphA2 level in HER2-negative breast cancer cells." (PMID 37816703, 2023). "In estrogen receptor-negative human breast carcinoma cells usually overexpressing ErbB2, it was demonstrated that the addition of EGF induced the translocation of Akt and CaM to the plasma membrane, where the activation of Akt occurs." (PMID 36979639, 2023). "Future efforts should look to validate the high PPV of ERBB2 CNG by NGS for HER2-positive IHC/FISH in breast cancer and other tumor types and subsequently whether ERBB2 CNG is predictive of benefit from HER2-targeted therapy." (PMID 35126865, 2022). "In breast cancer, the currently approved anti‐receptor tyrosine‐protein kinase erbB‐2 (HER2) therapies do not fully meet the expected clinical goals due to therapy resistance." (PMID 34564954, 2022). "The antibody–drug conjugate of trastuzumab deruxtecan against Her2 has shown activity in clinically Her2 negative breast cancers with low Her2 expression (i.e., IHC 1 + or 2 + with lack of ERBB2 amplification)." (PMID 36050786, 2022). "Focusing on our 22 breast cancer samples, 13 patients had received Anti-HER2 ERBB2 (Human Epidermal Growth Factor Receptor 2) gene therapy, despite only 11 showing HER2 ERBB2 positivity in their primary tumor samples, and ten of these showing the same positivity in their metastatic tumors." (PMID 36507516, 2022).
breast cancer (continued). "We further observed that trastuzumab, a therapeutic anti-ErbB2 antibody, upregulates BLNK in human trastuzumab-sensitive but not trastuzumab-resistant ErbB2-positive breast cancer cells." (PMID 35933456, 2022). "Although several spliced isoforms for breast cancer genes such as ESR1 and ERBB2 have been previously identified, current annotations widely used for transcriptome analysis, such as RefSeq and GENCODE, do not contain the level of complexity revealed by our LR-seq analysis." (PMID 35044822, 2022). "In vitro cellular uptake, a study was also conducted for tamoxifen citrate loaded nanoliposomes conjugated with antibody (FITC anti-human CD 340 (erbB2/HER-2)) in MCF-7 and MDA-MB-453 breast cancer cells at different concentrations, such as 50 and 100 μg/mL for 1 and 2 h, respectively." (PMID 35745897, 2022). "This cohort study included 2295 patients with ER-positive, ERBB2-negative breast cancer who had undergone a multigene assay between March 29, 2010, and December 31, 2020, in 2 hospitals." (PMID 36441548, 2022). "Intriguingly, higher ERBB3 expression levels correlate with lower relapse-free survival in basal-like/triple-negative (HER2-/ER-/PR-) breast cancer patients, and NRG1/ERBB3/ERBB2 axis was shown to promote anchorage-independent cell growth in basal-like/triple-negative breast cancer cells." (PMID 35664762, 2022). "Invasive lobular breast cancer (ILC) is a special breast cancer (BC) subtype and is mostly hormone receptor (HR)-positive and ERBB2 non-amplified." (PMID 35842479, 2022). "TNBC accounts for 10%-20% of breast cancer and characterized by the lack of traditional therapeutic targets, including estrogen receptor, progesterone receptor, and ErbB-2/HER-2/neu." (PMID 35992877, 2022). "ERBB2 is HER2, a member of the epidermal growth factor receptor (EGFR) family which is often overexpressed in breast cancer and an effective drug target in treating HER2-positive breast cancer." (PMID 35681777, 2022). "While HER2 is considered the main oncogene within this amplicon, studies have shown that some ERBB2-amplified breast cancer cell lines are not truly addicted to the HER2 oncogene but require other genes for survival against therapeutic challenge." (PMID 36139701, 2022). "As an example, for the early detection of breast cancer, ERBB2, human epidermal growth factor receptor 2 was functionalized through EDC-NHS chemistry on the surface of a graphene foam modified with electrospun carbon-doped titanium dioxide nanofibers (nTiO2) and GO–gold nanoparticles." (PMID 35743245, 2022). "Thus, future studies of ERBB2 CNG by ctDNA and HER2 IHC/FISH tissue correlation in both breast and non-breast cancer are needed." (PMID 35126865, 2022). "In breast cancer cells, Ras expression was reflected in high mitogen-activated protein kinase (MAP kinase) activity as well as EGFR (Epidermal Growth Factor Receptor) and erbB-2 overexpression." (PMID 35453754, 2022). "Triple-negative breast cancer (TNBC), which represents approximately 15% of all breast cancers, is characterized by the absence of estrogen receptor (ER), progesterone receptor (PR), and erb-b2 receptor tyrosine kinase 2 (ERBB2/HER2) expression." (PMID 35216080, 2022). "The Food and Drug Administration (FDA) approved the neratinib but not yet SYD985 in later-line setting for patients with ERBB2-positive advanced breast cancer in the US." (PMID 36159262, 2022). "In the US and China, margetuximab plus chemotherapy is not likely to be cost-effective for women with pretreated ERBB2-positive advanced breast cancer, whereas price reduction effectively improves insufficient cost-effectiveness." (PMID 36159262, 2022). "There are three major subtypes of breast cancer, depending on the presence or absence of molecular markers for progesterone or estrogen receptors, and human epidermal growth factor 2 (ERBB2)." (PMID 35209095, 2022).
breast cancer (continued). "Triple-negative breast cancer is another type of breast cancer characterized by the lack of expression of targets, such as progesterone receptor (PR), ER, or ERBB2; It makes up approximately 15% of all breast cancers." (PMID 36421127, 2022). "Conversely, breast cancers expressing ER and/or PR, but not ERBB2/HER2, are termed “hormone receptor-positive”, “hormone responsive” or “luminal” tumors." (PMID 35406375, 2022). "In contrast, the low annual incidence of BRM among patients with HR-positive/ERBB2-negative breast cancer would not justify screening for intracranial metastatic disease in this patient population." (PMID 35960523, 2022). "Our data suggested that the treatment of HER2+ breast cancer cells with NRG1 may sustain or restrain cell proliferation, as well as reduce the efficacy of ERBB2 targeting agents." (PMID 35664762, 2022). "Subtyping of breast cancer by complementing IHC tests with genomic tests for determining the ER (ESR1), PR (PGR), and HER2 (ERBB2) status could provide accurate classification results and further treatment of the patients can be based on the subtyping." (PMID 35006257, 2022). "ERBB2 somatic mutations are observed in 2–5% of primary breast cancers and most have been reported in HER2-negative breast cancers." (PMID 36029565, 2022). "However, for non-breast cancer cases, the PPV of ERBB2 amplification by tissue NGS dropped to 76% (n = 22) and by ctDNA to 44% (n = 7)." (PMID 35126865, 2022). "In this single-arm, phase 2, nonrandomized clinical trial of 67 patients with ERBB2-positive early breast cancer, the overall pathologic complete response rate of 6 cycles of neoadjuvant PATH regimen was 61%." (PMID 35797012, 2022). "Breast cancer is ordered into 4 major subtypes based on the presence or absence of molecular markers for estrogen receptors (ER) or progesterone receptors (PR) and human epidermal growth factor 2 (ERBB2; formerly HER2)." (PMID 35941873, 2022). "In metabolic alterations, transcriptional factors ERRs and their coactivators PGC-1s contribute to breast cancer progression and metastasis by modulating the transcription of their targets including OXPHOS-related genes and oncogenic genes, such as ERBB2 and MYC." (PMID 35178385, 2022). "The delay of the initiation of AHT past 150 days was associated with diminished survival in hormone receptor–positive, ERBB2-negative patients with breast cancer who did not receive chemotherapy." (PMID 35166783, 2022). "In subsequent phase III trials, abemaciclib was initiated at 200 mg BID for patients with KRASmut NSCLC and at 150 mg BID for patients with ERBB2-negative breast cancer." (PMID 36291780, 2022). "Moreover, GSDMB gene is frequently co-amplified with ERBB2/HER2 oncogene in breast and gastro-esophageal carcinomas, and in HER2+ breast cancers GSDMB upregulation promotes tumor aggressiveness and resistance to anti-HER2 therapies." (PMID 35281099, 2022). "In this NCDB cohort study, 6.4% of patients with HR-positive, ERBB2-negative breast cancer experienced a delay in initiating AHT longer than 150 days, which was significantly associated with poorer survival." (PMID 35166783, 2022). "Historical breast cancer classification is largely based on the cancer driver activity of ERα along with other hormone receptors, progesterone receptor (PR) and receptor tyrosine kinase HER2/ERBB2." (PMID 34497382, 2022).
breast cancer (continued). "AFAP1-AS1 (lncRNA) is transferred to breast cancer cells after being encapsulated by exosomes, leading to up-regulation of HER-2 expression and induction of trastuzumab resistance in BCCs by promoting AUF1-mediated ERBB2 translation activation." (PMID 36005690, 2022). "Surprisingly, despite a generally favorable prognosis of women with metastatic HR-positive/ERBB2-negative breast cancer with median survival now exceeding 5 years, survival among that subgroup in our study was relatively short." (PMID 35960523, 2022). "Our observational study noted a weakly positive correlation between BMI and RS in patients with ER-positive, ERBB2-negative breast cancer aged 45 years or younger." (PMID 36441548, 2022). "Furthermore, treatment with ErbB2- and EGFR-specific TKI lapatinib reduced P-PKM2 Tyr105 levels in a breast cancer mouse model." (PMID 35054968, 2022). "The results indicated that the prognosis of the patients with ERBB2 fusions was significantly worse than those without ERBB2 fusions in pan-cancer and breast cancer." (PMID 36276102, 2022). "Triple negative breast cancers (TNBCs) are a relatively heterogeneous breast cancer subtype, broadly characterised by the absence of the oestrogen receptor (ER), progesterone receptor (PR) and HER2 (ERBB2), found in other subtypes of the disease." (PMID 35768547, 2022). "According to the character of biomarkers, breast cancer is divided into three subtypes: hormone receptor-positive/ERBB2 negative, ERBB2 positive and triple negative." (PMID 35980268, 2022). "Several studies have looked at the expression of genes known to be important in breast cancer in humans, such the tyrosine kinase receptor proto-oncogene RON, and the ERBB2 proto-oncogene (also known as HER2, neu), to determine if they also show altered expression in feline mammary tumours." (PMID 36288160, 2022). "ERBB2-low (ie, ERBB2 immunohistochemistry score of 1+ or 2+ in the absence of ERBB2 gene amplification) breast cancer (BC) is a new entity, with emerging dedicated treatments." (PMID 36107428, 2022). "Triple-negative breast cancer (TNBC) is a definition encompassing all breast cancers with no/low immunohistochemically detectable expression of estrogen receptor α and progesterone receptor, and a lack of genomic amplification of ERBB2/HER2." (PMID 34684657, 2021). "The authors further show that ErbB2-overexpressing breast cancer cells with low CHIP expression exhibit higher ER stress inducibility, and ER stress-inducing anticancer drug Bortezomib synergizes with ErbB2-targeted humanized antibody Trastuzumab to inhibit cancer cell proliferation." (PMID 34439093, 2021). "As a consequence of the wide range of available treatments that target the Human epidermal growth factor receptor 2 (HER2), identifying either HER2 expression or ERBB2 gene amplification in tumor tissue is of great impact for the management of breast cancer patients." (PMID 35008244, 2021). "The p.I767M mutation in ERBB2 has not been described as oncogenic, but has been studied in breast cancer, and appeared sensitive to conventional anti-ERBB2 drugs." (PMID 34198671, 2021). "The study population comprised 565 postmenopausal women (mean [SD] age, 62.0 [5.3] years) with lymph node–negative, ER-positive/ERBB2-negative breast cancer." (PMID 34190995, 2021). "Interestingly, in breast cancer cells exhibiting a strong promoting role of CD151, receptor tyrosine kinases (RTKs) (e.g., EGFR, ErbB2, c-Met and Ron) or K-Ras are frequently activated because of gene amplification/overexpression or mutations." (PMID 33919420, 2021). "In addition, inhibition of the ERBB2 pathway with a neutralizing antibody or small-molecule inhibitor for ERBB2 normalizes CDKN1B expression, leading to cell cycle arrest in human breast cancer cells." (PMID 33585479, 2021).